IDE (insulin degrading enzyme)
Description:
Plays a role in the cellular breakdown of insulin, APP peptides, IAPP peptides, natriuretic peptides, glucagon, bradykinin, kallidin, and other peptides, and thereby plays a role in intercellular peptide signaling. Substrate binding induces important conformation changes, making it possible to bind and degrade larger substrates, such as insulin. Contributes to the regulation of peptide hormone signaling cascades and regulation of blood glucose homeostasis via its role in the degradation of insulin, glucagon and IAPP (By similarity). Plays a role in the degradation and clearance of APP-derived amyloidogenic peptides that are secreted by neurons and microglia (Probable). Degrades the natriuretic peptides ANP, BNP and CNP, inactivating their ability to raise intracellular cGMP. Also degrades an aberrant frameshifted 40-residue form of NPPA (fsNPPA) which is associated with familial atrial fibrillation in heterozygous patients. Involved in antigen processing. Produces both the N terminus and the C terminus of MAGEA3-derived antigenic peptide (EVDPIGHLY) that is presented to cytotoxic T lymphocytes by MHC class I. (Microbial infection) The membrane-associated isoform acts as an entry receptor for varicella-zoster virus (VZV).
Synonyms: INSULYSIN
Tractability: Small molecule: a structure with a bound ligand is known; a high-quality ligand is known; it has a binding pocket of medium quality; it belongs to a druggable protein family. Antibody: UniProt places it where antibodies can reach, with high confidence; its Gene Ontology location is reachable by antibodies, with medium confidence. PROTAC: ubiquitination databases record sites on it; its protein half-life has been measured; a small molecule that binds it is known.
Target class: Enzyme
Chemical probes: ML345
Gene: Protein-coding gene on chromosome 10 (92,451,684 to 92,574,096, reverse strand). Ensembl gene ENSG00000119912.
Subcellular location: Cytoplasm, cytosol; Cell membrane; Secreted
Pathways (Reactome):
Metabolism of proteins: Ub-specific processing proteases
Protein localization: Peroxisomal protein import
Signal Transduction: Insulin receptor recycling
Gene Ontology:
Molecular function: ATP binding; endopeptidase activity; insulin binding; metalloendopeptidase activity; peptide binding; protein binding; protein homodimerization activity; zinc ion binding; amyloid-beta binding; ATP hydrolysis activity; beta-endorphin binding; identical protein binding; metal ion binding; peptide hormone binding; protein-containing complex binding
Biological process: amyloid-beta clearance; amyloid-beta clearance by cellular catabolic process; amyloid-beta metabolic process; antigen processing and presentation of endogenous peptide antigen via MHC class I; bradykinin catabolic process; hormone catabolic process; insulin catabolic process; insulin metabolic process; peptide catabolic process; positive regulation of protein binding; protein catabolic process; proteolysis; regulation of aerobic respiration; ubiquitin recycling; insulin receptor signaling pathway; positive regulation of protein catabolic process; negative regulation of proteolysis
Cellular component: basolateral plasma membrane; cell surface; cytoplasm; cytosol; external side of plasma membrane; extracellular region; mitochondrion; nucleus; peroxisome; extracellular exosome; peroxisomal matrix; plasma membrane; cytosolic proteasome complex
Genetic constraint (gnomAD): Loss-of-function variants: 20 observed, 45.57 expected, observed/expected ratio (o/e) 0.44, 90% interval 0.31 to 0.64. The upper end of that interval is the gene's LOEUF score, 0.64, which puts it in group 2 of 6, group 1 being the genes least tolerant of losing a copy. Missense variants: 420 observed, 559.26 expected, observed/expected ratio (o/e) 0.75, 90% interval 0.69 to 0.81. Synonymous variants: 181 observed, 195.26 expected, observed/expected ratio (o/e) 0.93, 90% interval 0.82 to 1.05.
Homologues: Orthologues: chimpanzee IDE (99% identical), macaque IDE (99% identical), pig IDE (99% identical), guinea pig IDE (97% identical), dog IDE (96% identical), rabbit IDE (96% identical), rat Ide (95% identical), mouse Ide (95% identical), tropical clawed frog ide (90% identical), zebrafish ide (86% identical), Drosophila melanogaster Ide (45% identical), Caenorhabditis elegans F44E7.4 (41% identical), and 2 more. Paralogues in human: NRDC (35% identical), PITRM1 (13% identical), PMPCA (10% identical), PMPCB (10% identical), UQCRC1 (9% identical), UQCRC2 (8% identical).
Diseases named in the same sentence as IDE in open-access papers:
IDE is named in the same sentence as 52 diseases in open-access papers, as found by Europe PMC text mining. Sharing a sentence is not in itself a finding about the gene and the disease. The quoted sentences say what the papers report.
Alzheimer disease (54 papers, 2009 to 2025). A progressive, neurodegenerative disease characterized by loss of function and death of nerve cells in several areas of the brain leading to loss of cognitive function such as memory and language. "In human astrocytes, IDE serves as the principal protease for Aβ degradation, and its dys-regulation is a hallmark of Alzheimer’s disease (AD)." (PMID 40385290, 2025). "Our study focused on the single nucleotide polymorphism (SNP) rs2421943 in the IDE gene, which has previously been associated with the pathogenesis of Alzheimer's disease." (PMID 37515308, 2023). "IDE is one of the major proteases of amyloid beta peptide (Aβ), presumed to be a causative molecule in Alzheimer disease (AD) pathogenesis." (PMID 31450711, 2019). "Insulin-degrading enzyme (IDE) is a zinc metalloprotease that selectively degrades biologically important substrates associated with type 2 diabetes and Alzheimer’s disease (AD)." (PMID 30305381, 2018). "The IDE gene is located on chromosome 10q23.3 close to a region of linkage for the late-onset Alzheimer's Disease susceptibility genome." (PMID 28070499, 2017). "It is here that we see the link between T2DM and Alzheimer disease pathology: brain insulin deficiency results in the down-regulation of insulin degrading enzyme (IDE; Luchsinger, 2008), which also has a role in degrading Aβ." (PMID 25071557, 2014). "Hypocatabolism of the amyloid β-protein (Aβ) by insulin-degrading enzyme (IDE) is implicated in the pathogenesis of Alzheimer disease (AD), making pharmacological activation of IDE an attractive therapeutic strategy." (PMID 19384407, 2009). "IDE is implicated in the pathogenesis of Alzheimer disease (AD) and type-2 diabetes mellitus, and has also been identified as the cellular receptor for varicella zoster virus infection and cell-to-cell spread." (PMID 19835587, 2009). "In addition, patients with Alzheimer’s disease have abnormal insulin metabolism associated with the apolipoprotein E,33 corroborated by reports of reduced hippocampal insulin-degrading enzyme (an amyloid-β-degrading metalloprotease) in APOE-ε4 carriers." (PMID 40834163, 2025). "Alzheimer's Disease (AD) and Type 2 Diabetes (T2D) are closely related to each other as both exhibit common metabolic disorders including zinc and insulin degrading enzyme (IDE) deficiencies." (PMID 28070499, 2017). "Insulin degrading enzyme (IDE) is a highly evolutionary conserved protease that has been involved in Insulin and amyloid-beta metabolism and consequentially associated to diabetes mellitus, metabolic syndrome, Alzheimer’s disease and amyloid angiopathy 34,35,36,37." (PMID 39866114, 2025). "Similarly, there is a well‐described association between Alzheimer's disease and IDE based on Aβ clearance, with the G allele of the rs2421943 polymorphism of the IDE gene being associated with an increased risk of Alzheimer's disease and mild cognitive impairment." (PMID 37515308, 2023). "Because of its close relationship with type 2 diabetes and Alzheimer’s disease, IDE has attracted much attention as a target for new drug development, but the mechanism of its binding with different targets has not been clear." (PMID 39908369, 2025). "IDE is thought to be a potential therapeutic target for type-2 diabetes and neurodegenerative diseases, such as Alzheimer’s disease." (PMID 35163673, 2022). "Increased insulin level in the brain contributes to Alzheimer’s Disease pathology, as the insulin-degrading enzyme (IDE) also takes part in degrading senile plaques, and in insulin resistance, it is involved in degrading insulin." (PMID 34885795, 2021). "Identification of PIF-interacting cofactors is currently underway as in the case of insulin-degrading enzyme in Alzheimer disease." (PMID 34676826, 2021). "Insulin degrading enzyme (IDE) is a M16 zinc-metalloprotease that selectively degrades amyloidogenic peptides such as amyloid β, peptide vital for the progression of Alzheimer’s disease." (PMID 25636406, 2015).
Alzheimer disease (continued). "Insulin degrading enzyme (IDE) is a major protease of amyloid beta peptide (Aβ), a prominent toxic protein in Alzheimer’s disease (AD) pathogenesis." (PMID 26520569, 2015). "The insulin-degrading enzyme (IDE) degrades amyloidogenic proteins such as Amyloid β (Αβ) and Islet Amyloid Polypeptide (IAPP), i.e. peptides associated with Alzheimer’s disease and type 2 diabetes, respectively." (PMID 26228656, 2015). "We previously reported that Alzheimer disease (AD) model mice showed decreased insulin-degrading enzyme (IDE) levels in the cerebrum and accelerated phenotypic features of AD when crossbred with alpha-tocopherol transfer protein knockout (Ttpa-/-) mice." (PMID 26637123, 2015). "For example, IDE knockout mice have been shown to develop diabetic phenotype, whereas overexpression of IDE in Alzheimer's disease mouse models have been shown to completely eliminate amyloid plaque formation and downstream cytopathology." (PMID 22355395, 2012). "Insulin-degrading enzyme (IDE) is a thiol sensitive peptidase that degrades insulin and amyloid β, and has been linked to type 2 diabetes mellitus and Alzheimer's disease." (PMID 21448434, 2011). "Insulin degrading enzyme (IDE) is responsible for the metabolism of insulin and plays a role in clearance of the Aβ peptide associated with Alzheimer's disease." (PMID 21731629, 2011). "The insulin-degrading enzyme gene (IDE) is a strong functional and positional candidate for late onset Alzheimer's disease (LOAD)." (PMID 20098734, 2010). "Insulin-degrading enzyme (IDE) is a widely studied zinc-metalloprotease implicated in the pathogenesis of type 2 diabetes mellitus, Alzheimer disease (AD) and varicella zoster virus infection." (PMID 19835587, 2009). "IDE also plays a significant role in the degradation and clearance of amyloidogenic peptides derived from APP secreted by neurons and microglia, and a deficiency in the function of this protein is associated with Alzheimer’s disease." (PMID 39456746, 2024). "Insulin degrading enzyme (IDE) plays a critical role in degrading insulin and beta-forming proteins, implicating its significance as a biomarker in metabolic dysfunction and neurocognitive disorders, including Alzheimer's disease (AD)." (PMID 38812908, 2024). "Besides insulin, IDE is able to cleave many substrates in vitro, including amyloid beta peptides, making this enzyme a candidate pathophysiological link between Alzheimer's disease (AD) and type 2 diabetes (T2D)." (PMID 37817156, 2023). "Besides insulin, IDE is involved in the degradation of amyloidogenic proteins (e.g., β-amyloid), providing evidence of its involvement in Alzheimer’s disease (AD) pathogenesis." (PMID 35204815, 2022). "IDE is a zinc metalloprotease that is present in the cytosol of all cells, degrades many small proteins, including insulin and amyloid, and is also involved in the pathogenesis of diabetes and Alzheimer’s disease (AD)." (PMID 35992696, 2022). "IDE has been discussed as a potential target for both diabetes and Alzheimer’s disease." (PMID 32328086, 2020). "A reduction of IDE activity in the brain with age and during the early stages of Alzheimer’s disease (AD) has been observed, suggesting that IDE downregulation may be among the triggers of AD." (PMID 31547034, 2019). "Insulin degrading enzyme (IDE) is believed to act as a junction point of Type 2 diabetes (T2D) and Alzheimer's disease (AD); however, the underlying mechanism was not completely clear yet." (PMID 29222348, 2018). "It is now thought that a contributing factor in cases of sporadic, late-onset Alzheimer’s disease may be a deficiency in the catabolism of the Aβ peptide by enzymes such as neprilysin (NEP) and insulin-degrading enzyme (IDE)." (PMID 23555730, 2013).
Alzheimer disease (continued). "Regarding the GHRH-GH-IGF axis, MIA-690 decreased the secretion of IGF-I in the supernatant of HCN-2 cell cultures which is critical since in Alzheimer's disease one of the most important pathologic phenomena, is the competition of insulin and amyloid-β for insulin-degrading enzyme (IDE)." (PMID 23211425, 2012). "IDE, originally known as the main enzyme involved in the cleavage of insulin as well as other amyloidogenic peptides, such as the β-amyloid (Aβ) peptide, eliminates Aβ’s neurotoxic effects, one of the hallmarks of Alzheimer’s disease (AD), which shows the relationship between IDE, diabetes, and AD." (PMID 40943177, 2025). "In animal models of Alzheimer’s disease, physical exercise—including resistance training and multimodal programs—has been shown to reduce Aβ levels and accumulation, as well as increase the activity or expression of degrading enzymes such as neprilysin and IDE." (PMID 41373296, 2025). "Because reduced IDE function has been implicated in the pathogenesis of both T2DM and Alzheimer disease, these studies lend support the notion that pharmacological upregulation of IDE might represent viable therapeutic strategies for the treatment of both diseases." (PMID 33477364, 2021). "Amylin, a gut-brain axis hormone, and amyloid-beta peptides (Aβ), a major component of the Alzheimer's disease (AD) brain, share several features, including similar β-sheet secondary structures, binding to the same receptor and being degraded by the same protease, insulin degrading enzyme (IDE)." (PMID 25120481, 2014). "The insulin-degrading enzyme (IDE) plays a significant role in the degradation of the amyloid beta (Aβ), a peptide found in the brain regions of the patients with early Alzheimer's disease." (PMID 41674878, 2024). "This study aimed to explore correlations between insulin-degrading enzyme (IDE) and markers of metabolic function in a group of patients diagnosed with type 2 diabetes mellitus (T2DM) or Alzheimer’s disease (AD) and metabolically healthy volunteers." (PMID 37980298, 2024). "Insulin Degrading Enzyme (IDE) is a protease conserved through evolution with a role in diabetes and Alzheimer's disease." (PMID 23826334, 2013). "Insulin-degrading enzyme (IDE) is an allosteric Zn+2 metalloprotease involved in the degradation of many peptides including amyloid-β, and insulin that play key roles in Alzheimer's disease (AD) and type 2 diabetes mellitus (T2DM), respectively." (PMID 22355395, 2012). "Treadmill exercise significantly improved learning and memory, reduced Aβ plaques and sAβ1–42 in the brain and blood, and upregulated the expression of NEP, IDE, and LRP-1 in a rat model of Alzheimer’s disease, with statistically significant differences (p < 0.05 to p < 0.001)." (PMID 40161268, 2025). "In our previous study, we developed a liquid natural ECM biomaterial enriched with insulin-degrading enzyme (IDE) and membrane metalloendopeptidase (MME) to reduce amyloid-beta (Aβ) peptide accumulation and Tau phosphorylation in Alzheimer’s disease cell models." (PMID 34938180, 2021). "More and more research is focusing on the role IDE (insulin-degrading enzyme) in modulate insulin level, arising amyloid β (Aβ) and development of cognitive impairment characteristic for the type 2 diabetes mellitus (T2DM) and Alzheimer’s disease." (PMID 33918576, 2021). "Besides this, strategies to inhibit the insulin-degrading enzyme (IDE) have also been proven to be beneficial in the case of T2DM and Alzheimer’s disease (A.D) and alterations of the levels of insulin in the cytosol." (PMID 30347680, 2018).